ENSG00000277067 (novel transcript)
Synonyms: LOC102724843
Gene: Long non-coding RNA gene on chromosome 21 (7,048,748 to 7,116,635, forward strand). Ensembl gene ENSG00000277067.
Homologues: Paralogues in human: LINC03105 (100% identical).